ABCG2 (ATP binding cassette subfamily G member 2 (JR blood group))
Diseases named in the same sentence as ABCG2 in open-access papers (continued):
Sharing a sentence is not in itself a finding about the gene and the disease.
colorectal cancer (continued). "Among ABC transporters, P-glycoprotein (P-gp), multidrug resistance-associated protein 1 (MRP1 or ABCC1), and ATP-binding cassette subfamily G member 2 (ABCG2) have been studied for their implication in MDR, with great relevance for colorectal cancer." (PMID 37092502, 2023). "Sensitivity and specificity analysis found that ABCG2 expression could be a good discriminator between cancerous and adjacent noncancerous tissues in both colon and rectum adenocarcinomas, and it may hence be potentially useful as a colorectal cancer biomarker." (PMID 37445716, 2023). "Hence, it can be suggested that the downregulation of ABCG2 expression observed in colorectal cancer can result from inflammation in the bowel mucosa, and that this may represent a preliminary step in reducing its protective potential against cancer-promoting xenobiotics." (PMID 37445716, 2023). "Mutual regulation has also been confirmed in other studies, indicating that increased expression of both ABCG2 and EGFR (metastatic marker) is positively correlated with resistance to anoikis and metastatic potential in the colorectal cancer cell population." (PMID 37445716, 2023). "We recently analytically validated commercial antibodies for immunohistochemical (IHC) staining of ABCG2 on formalin-fixed formalin embedded colorectal cancer tissue and identified the BXP21 antibody to fulfill requirements for ABCG2 IHC." (PMID 32326511, 2020). "Breast cancer resistance protein, also called ABCG2, is crucial for multidrug resistance (MDR) mechanism in colorectal carcinoma." (PMID 30380774, 2018). "The treatment of colorectal cancer (CRC) includes surgery and combination therapy regimes containing ABCG2 substrates such as 5FU and irinotecan." (PMID 27257141, 2016). "In wet analysis of colorectal cancer samples, neither ABCG2 gene expression, analysed by RT-PCR, nor ABCG2 protein level, assessed by immunohistochemistry, was associated with any clinicopathological factors or overall survival." (PMID 37445716, 2023). "In contrast, higher expression of ABCG2 protein has been reported in colorectal cancer tissue than in non-carcinomatous margin tissues." (PMID 37445716, 2023). "siRNA-mediated knock-down of ABCG2 expression lowered the self-renewal capacity of the cells and increased the efficiency of chemotherapy-induced apoptosis in colon adenocarcinoma cells and CD133-positive colorectal carcinoma cells." (PMID 37445716, 2023). "Moreover, in colorectal cancers, overexpression of ABCB1 and ABCG2 has been documented with poor clinical outcome." (PMID 33593355, 2021). "Of specific interest is that the resistance mechanisms in our three oxaliplatin-resistant colorectal cancer cell lines did not include regulation of ABCG2 or TOP1 mRNA." (PMID 32326511, 2020). "Similarly, ABCG2 and ABCB1 were reported to be up-regulated in the response to combined 5-FU and irinotecan treatment in SW480 colorectal carcinoma cell line concomitant with the activation of Wnt signaling." (PMID 32456134, 2020). "Furthermore, four genes, ABCG2, PADI2, CA7, and TGFBI, have been verified in previous studies as potentially correlated with colorectal cancer." (PMID 28229027, 2017). "Moreover, PZH increased the accumulation of Rhodamine-123 and downregulated the drug resistance induced expression of ABCG2 in HCT-8/5-FU cells, thus demonstrating the inhibitory effect of PZH on chemoresistance of colorectal cancer cells." (PMID 25505925, 2014). "The low occurrence of the ACBG2 sequence and copy number changes in colorectal cancer indicates that they are unlikely to be responsible for ABCG2 underexpression, that another molecular mechanism is responsible for regulating the transcription of this gene in colorectal cancer." (PMID 37445716, 2023). "Moreover, overall survival did not correlate with ABCG2 protein or ABCG2 gene expression in our colorectal cancer cohort." (PMID 37445716, 2023).
colorectal cancer (continued). "In the present study, we found that AZ32 could sensitize ABCG2-overexpressing colorectal cancer cells to mitoxantrone and doxorubicin but not cisplatin." (PMID 34094985, 2021). "In the absence of a clear connection with clinical parameters and prognosis, significant alterations in ABCG2 gene and protein expression in colorectal cancer may suggest that ABCG2 has a complex role in tumorigenesis that is not directly or solely related to its transport function." (PMID 37445716, 2023). "However, at nearly non-toxic concentration, gedatolisib could not significantly reverse ABCB1- or ABCG2-medaited MDR in colorectal cancer cells, indicated that gedatolisib could not be a good reversal agent due to its relative high toxicity." (PMID 33593355, 2021). "In conclusion, ML210 can sensitize ABCB1-overexpressing multidrug-resistant colorectal cancer cells to ABCB1-substrate chemotherapeutic agents, indicating that ML210 is a promising ABCB1 inhibitor capable of antagonizing ABCB1- not ABCG2-mediated MDR in CRC." (PMID 40427071, 2025).
pancreatic cancer (78 papers, 2011 to 2026). "Several studies examining the importance of ABC-transporters in gemcitabine resistance have confirmed that the abnormal expression of ABCB1, ABCC, and ABCG2 is associated with multidrug-resistance in pancreatic cancer." (PMID 35582220, 2020). "Furthermore, liraglutide enhances the susceptibility of gemcitabine-resistant pancreatic cancer cells to apoptosis by downregulating ATP-binding cassette transporter G2 (ABCG2) via NF-κB signaling." (PMID 40140925, 2025). "For pancreatic cancer, a recent study in pancreatic cancer survivors found that a single nucleotide polymorphism (SNP) in ABCG2 (rs2231164) correlated with pancreatic cancer survival; patients carrying the AG/GG genotypes exhibited better survival than those carrying the AA genotype." (PMID 24883056, 2014). "In addition, another critical role of PSCs in PDAC progression has been documented to be associated with the pancreatic cancer-stem-cell through enhancing the spheroid-forming ability of cancer cells and inducing the expression of cancer stem cell-related genes ABCG2, Nestin, and LIN28." (PMID 24587996, 2014). "For example, ABCG2 was found to be overexpressed in CSCs from pancreatic cancer and other tumoral malignancies, where it pumps in and accumulates ABCG2-dependent substrates and drugs, such as Mitoxantrone." (PMID 41148824, 2025). "A previous study with BPD demonstrated the downregulation of ABCG2 expression at a low PDT dose with an improved uptake of irinotecan in human pancreatic cancer cells." (PMID 39403604, 2024). "In pancreatic cancer, ABCG2, ABCC1, ABCC5, and ABCA8 have been specifically reported to be associated with gemcitabine resistance, whereas additional ABC transporters are widely expressed in chemoresistant PDAC cells." (PMID 39000545, 2024). "Treatment of pancreatic cancer cells with SGC707 significantly reduced the expression of ABCG2, which sensitised the cells to gemcitabine." (PMID 39703687, 2024). "For instance, the overexpression of PRMT3 led to gemcitabine resistance in pancreatic cancer cells by upregulating the expression of the drug transporter ABCG2." (PMID 39703687, 2024). "For example, pancreatic cancer cells with autophagy blockade exhibited low glucose uptake and expressed low levels of ATP-binding cassette sub-family G member 2 (ABCG2) in the secreted exosomes, which restored gemcitabine sensitivity." (PMID 36588730, 2022). "Similar resistance was observed in other pancreatic cancer lines, BxPC-3 and MiaPaca-2, with ABCG2 overexpression." (PMID 34049503, 2021). "The knockdown of GIPC in pancreatic cancer cells induces the overexpression and incorporation into exosomes of the ATP-binding cassette sub-family G member 2 (ABCG2)." (PMID 34283059, 2021). "The activation of the bitter taste receptor TAS2R10 by caffeine in pancreatic cancer cell lines affected different signalling pathway molecules including the downregulation of ABCG2, a protein promoting multidrug resistance." (PMID 34885005, 2021). "Previous studies report that PRMT3 enhances chemoresistance by upregulating ABCG2 expression and by inducing metabolic reprogramming in pancreatic cancer." (PMID 34753906, 2021). "Through downregulating ABCG2, hsa-miR-520h inhibits cell migration, invasion, and side populations from pancreatic cancer 26-28." (PMID 34659544, 2021). "Meanwhile, ABCB1 and ABCG2 were found to be an important indicator of drug-resistance in pancreatic cancer." (PMID 31652737, 2019). "In order to further confirm the protein expression results in vitro, the immunohistochemical analysis was assessed for ABCB1 and ABCG2 expression levels in pancreatic tumor tissues from xenograft mice." (PMID 31652737, 2019). "Together, these data suggested that upregulation of ABCG2 expression by PRMT3 contributes to GEM resistance in pancreatic cancer." (PMID 30577570, 2018).
pancreatic cancer (continued). "Functional studies have indicated that loss of miR-520h expression is accompanied by subsequent activation of ABCG2 expression, which represent critical events in the invasion and migration of human pancreatic cancer cells." (PMID 28182660, 2017). "In the pancreatic cancer, there are significant correlations between mRNA levels of ABCG2 and clinical outcomes." (PMID 28347288, 2017). "Strikingly, every pancreatic cancer cell line expressed ABCG2 by 2–5 fold above normal pancreatic epithelial cell lines, whereas none of the cells expressed MDR-1." (PMID 26859746, 2016). "PSCs enhance the cancer stem cell phenotype of pancreatic cancer cells by inducing the expression of genes such as ABCG2, Nestin and LIN28 leading to an enhanced radio-resistance of pancreatic cancer cells in in vitro and in vivo systems of pancreatic cancer." (PMID 26029109, 2015). "To verify the role of ABCG2 in drug sensitivity, we tested gemcitabine, a frontline pancreatic cancer drug, at different concentrations in GIPC-depleted PANC-1 cells." (PMID 25469510, 2014). "In pancreatic cancer cell lines, ABCG2 was also found to be upregulated in the SP and associated with chemotherapy resistance." (PMID 22894607, 2012). "Human pancreatic CSCs expressing high levels of CD133, CD24, CD44, ESA, and aldehyde dehydrogenase also express significantly more Nanog, Oct-4, Notch1, MDR1 and ABCG2 than normal pancreatic tissues and primary pancreatic cancer cells." (PMID 21304978, 2011). "Normal pancreatic tissues express very low levels of CD133, CD24, CD44, ESA, Nanog, Notch1, MDR1 and ABCG2 compared to pancreatic cancer and CSCs." (PMID 21304978, 2011). "In an in vitro setup, we have also demonstrated that stemness-like state can be achieved in the presence of Cyr61 through the regulation of multiple stemness traits including ABCG2, Notch-1, Oct-4 and CD-44 in pancreatic cancer cells." (PMID 21232118, 2011). "For instance, hypoxia induces extracellular signal-regulated kinase 1/2 (ERK1/2) phosphorylation to activate HIF-1α, which directly binds to the promoter of ABCG2 gene and subsequently enhances ABCG2 transcription, leading to gemcitabine chemoresistance in pancreatic cancer cells." (PMID 40612109, 2025). "Adlay seed extract could increase the efficacy of gemcitabine therapy and mitigate its upregulation of ABCB1 and ABCG2 proteins in pancreatic cancer cells, due to the alteration of the ABC transporter-mediated drug efflux function." (PMID 35956759, 2022). "We confirmed ABCG2 overexpression in three pancreatic cancer lines resulted in resistance to chemotherapy and we showed that chemical inhibition of ABCG2 can reverse resistance in vitro, but its clinical relevance is unclear given a lack of strong correlation with patient outcomes." (PMID 34049503, 2021). "In addition, ABCB1 and ABCG2 transporter mainly expresses in cell membranes and cytoplasm in pancreatic cancer cells." (PMID 31652737, 2019). "Additionally, the multidrug transporter ABCG2 has been shown to be downregulated following PDT in orthotopic in vivo models of pancreatic cancer, leading to increased irinotecan retention and therapeutic efficacy." (PMID 29560127, 2018). "Moreover, it has been shown that miR-520h functions as a potent suppressor of migration and invasion of human pancreatic cancer cells through down-regulation of ABCG2 expression." (PMID 28182660, 2017). "Knockdown of PIM-1 expression in pancreatic cancer cells suppressed proliferation, induced cell cycle arrest, enhanced apoptosis, resensitized cells to gemcitabine and erlotinib treatment, and inhibited ABCG2 and EZH2 mRNA expression." (PMID 27596051, 2016). "We found that PIM-1 knockdown in pancreatic cancer cells suppressed proliferation, induced cell cycle arrest, enhanced apoptosis, resensitized cells to gemcitabine and erlotinib treatment, and inhibited ABCG2 and EZH2 mRNA expression." (PMID 27596051, 2016).
pancreatic cancer (continued). "Furthermore, we have shown the overexpression of the drug resistance gene ABCG2 in exosomes from GIPC-depleted pancreatic cancer cells." (PMID 25469510, 2014). "Additionally, it was reported that hsa-miR-520 h downregulates ABCG2 in pancreatic cancer cells leading to inhibition of migration, invasion, and side population cells." (PMID 22952907, 2012). "We have recently demonstrated that pancreatic CSC's expressing stem cells markers CD133, CD44, CD24, ESA, express high levels of pluripotency maintaining factors, and drug resistance genes MDR1 and ABCG2 as compared to normal pancreatic cells and pancreatic cancer cells." (PMID 23029396, 2012). "Interestingly, Pancreatic CD44+ESA+CD133+CD24+ CSCs also expressed CK19 (pancreatic cancer specific epithelial marker) and ABCG2 drug resistance genes." (PMID 23029396, 2012). "We next examined the expression of stem cell markers (CD133+CD44+CD24+ESA+), pluripotency maintaining factors (Nanog), signaling molecule (Notch-1) and drug resistant genes (MDR1 and ABCG2) in human normal pancreas, primary pancreatic cancer cells, and CSCs by q-RT-PCR." (PMID 21304978, 2011). "In pancreatic cancer cells, GIPC facilitates vesicular transport or membrane stabilization of ABCG2, which promotes ABCG2 release from intracellular vesicles." (PMID 41522336, 2026). "In pancreatic cancer, PRMT3 enhances chemoresistance by methylating heterogeneous nuclear ribonucleoprotein A1 (hnRNPA1), which stabilizes ABCG2 mRNA." (PMID 40050608, 2025). "In conclusion, our findings show that FOXP1 plays an essential role in establishing chemoresistance in pancreatic cancer by enhancing CSC characteristics and upregulating ABCG2 expression." (PMID 40169859, 2025). "Since the substrate sets of ABCA1-2, ABCB1, ABCC5, and ABCG2 overlap, the general effect of SOX9 suppression on overall or partial drug resistance of pancreatic cancer cells in context of these ABC proteins cannot be predicted with certainty." (PMID 40141294, 2025). "ABCG2 and ABCB1 have been suggested as important mediators of resistance to chemotherapy (CTx) in pancreatic cancer (PC)." (PMID 40548120, 2025). "FOXP1 mediated chemoresistance in pancreatic cancer by directly regulating ABCG2, further validating the crucial role FOXP1 plays in modulating chemoresistance in pancreatic cancer." (PMID 40169859, 2025). "PRMT3 has been shown to regulate metabolic reprogramming in pancreatic cancers by methylating glycolytic pathway components such as GAPDH and ABCG2 to reprogram cellular metabolism to promote tumor progression." (PMID 36351894, 2022). "TGF-β1 has been reported to upregulate ABCG2 expression via the SMAD-dependent signaling pathway in various human cancers, including breast and pancreatic cancers." (PMID 35684095, 2022). "Further, GLRX3 knockdown reduced the level of ABCG2, EMT, and chemo-resistance related proteins in pancreatic cancer cells." (PMID 34794402, 2021). "Pancreatic cancer stem cells do exist and express specific markers including CXCR4, ABCG2, and CD44." (PMID 32210079, 2020). "Immunofluorescence staining further showed that abundant ABCG2-positive or CD133-positive subpopulation cells in lung nodules expressed GLUT5, indicating that invasive pancreatic cancer subpopulations are able to efficiently take up fructose." (PMID 28032597, 2017). "In the current study, Sox2, Oct-4, ABCG2, and NANOG were simultaneously upregulated in miR-629-overexpressed pancreatic cancer cells, and the expression of p21 and p27 was inversely correlated with the expression of miR-629 in pancreatic cancer cells." (PMID 29072689, 2017). "We also investigated the expression levels of the pancreatic cancer stem cell markers ABCG2 and EZH2 by qRT-PCR, and we found that ABCG2 and EZH2 mRNA expression levels were significantly decreased following siRNA-mediated knockdown of PIM-1 expression." (PMID 27596051, 2016).